IL4 (interleukin 4)
Diseases named in the same sentence as IL4 in open-access papers (continued):
Sharing a sentence is not in itself a finding about the gene and the disease.
Allergy (continued). "TH2-related cytokine (IL-4) was increased by the allergy induction and inhibited by GA, especially at the dose of 100 mg/kg∙bw of GA." (PMID 28775294, 2017). "Return to IL-4 modulating the expression of CCL24 in allergy, many study focused the relationship of Rho GTPase family and Th2 cell factors." (PMID 28042950, 2017). "Review CCL24 research in allergy, some study invariably involved Th2 cell factors IL-4 or/and IL-13." (PMID 28042950, 2017). "On the other hand, Th2 cells induce interleukin-4 (IL-4) production to mediate the activation and maintenance of the humoral and/or allergy immune response against extracellular parasites, bacteria, allergens, and toxins." (PMID 28781969, 2017). "In B-lymphocytes, IL4 promotes immunoglobulin isotype-switching from IgG to IgE, and thereby contributes to the typical immune responses seen in allergy and asthma." (PMID 29232822, 2017). "BALB/c mice was chosen for generating the Dp allergy model as they have been shown to develop a vigorous Th2 response due to their inherent robust IL-4 production." (PMID 29182623, 2017). "The Th2 response that is characterized by production of IL-4, IL-5, IL-13 and IL-10, mediates anti-inflammatory responses, allergy, and fungal persistence in the lungs." (PMID 29371571, 2017). "In that study we found an interaction between interleukin 4 (IL4), a cytokine active in allergy and normal brain function), and its soluble receptor, interleukin 4 receptor alpha (sIL4RA)." (PMID 28594935, 2017). "A combination of anti-C3H and C3H anti‐anti-C3H IgG antibodies down-regulated inflammation in a mouse model of inflammatory bowel disease (>75%) and attenuated anti-IgE production and sensitization to produce IL4 cytokines (>70%) in an OVA-allergy model." (PMID 28679488, 2017). "The presented DCS device has been optimized to detect the onset of an allergic response and to sense the presence of IL-4 and IL-13 cytokines during the allergic disease." (PMID 29062109, 2017). "Active systemic allergic reaction in Balb/c mice showed that GA can suppress the increased level of IL-4 to restore the immune balance of TH1/TH2 cells in a dose-dependent manner." (PMID 28775294, 2017). "There were reports suggesting possible adverse side effects of IL-4, including pathological fibrosis, atherosclerosis and exacerbation of allergic diseases like asthma, raising concerns on its clinical application." (PMID 28761077, 2017). "Among children over 36 months, those in the recurrence group had more allergic disease and higher IgE, IL-4, and IL-5 levels than the same-aged children in control group." (PMID 28418014, 2017). "Once the early phase of the allergic reaction has developed into a chronic allergic inflammation, the production of IL-4 and IL-13 occurs in a positive feedback loop, which results in an increase in IgE levels." (PMID 29062109, 2017). "The Th2 cytokine IL-4, on the other hand, suppresses CTL function and stimulates a subset of B cells, thereby causing allergies." (PMID 27631416, 2016). "All Th2-related cytokines (IL-4, IL-5, IL-10, and IL-13) were increased by the allergy induction and inhibited by baicalein." (PMID 27561877, 2016). "Induction of allergy in the lungs via HDM resulted in an increase in mRNA for IL‐4, IL‐5, IL‐13 and IL‐17." (PMID 27059010, 2016). "One of the pathological features of allergic diseases is the over-production of T helper (Th) 2 cytokines, including IL-4, IL-5, IL-13, etc., in the sera and the local tissue." (PMID 27825134, 2016). "We demonstrated that pioglitazone treatment inhibited female Th2 differentiation by reducing both IL-4 and IL-13 production, which are important for allergic disease pathogenesis." (PMID 27548145, 2016). "Prompted by published data that levels of IL-13 are higher in allergic diseases and IL-13 modulates other gene transcription, we exposed B cells from healthy individuals to Th2 cytokines IL-4, or IL-5, or IL-13 in the culture." (PMID 27825134, 2016).
Allergy (continued). "Allergic diseases are sustained by a T-helper 2 polarization leading to interleukin-4 secretion, IgE-dependent inflammation, and mast cell and eosinophil activation." (PMID 27413762, 2016). "MGL has been reported to be a marker of alternative activation in murine models of allergy and parasitic infection, with IL-4 and IL-13 being shown to be crucial for its induction and maintenance." (PMID 25951175, 2015). "In a general view, allergy is a T helper 2 (Th2) cells-mediated disease that involves the hyperproduction of specific immunoglobulin E (IgE) antibodies to which interleukin-4 (IL-4) and IL-13, the key Th2-specific cytokines, mainly contribute." (PMID 26131770, 2015). "Inflammatory cytokines such as TNF-α, IL-1β, and IL-4 play crucial roles in prompting and sustaining chronic allergy." (PMID 26068872, 2015). "Dendritic cells of skin captured allergy to induce the overexpression of Th2 cells to secrete more the levels of IL-4 and IL-5." (PMID 25861366, 2015). "The tests were performed on 63 patients (24 women and 39 men) with chronic rhinosinusitis and polyps (CRSwP—study group I), with determination of the COX-2, POSTN and IL-4 gene expression; an allergy was diagnosed in 38 cases." (PMID 25573836, 2015). "On the contrary cell system, we can detect allergy associated cytokines such as TNF-α, IL-4, IL-13 by RT-PCR in vivo system." (PMID 26317642, 2015). "IL-4, IL-13, eotaxin, and CysLT play very important roles in allergy, and their concordant actions in bone-marrow suggest that IL-17A effects on bone-marrow are generally attenuated by mediators of allergy, in a way consistent with in vivo observations." (PMID 26199466, 2015). "The high expression of IL-4 gene in patients with CRS with Ps (CRSwP) was related to the presence of an allergy." (PMID 25573836, 2015). "Histamine upregulates Th2 cells proliferation and production of Th2 cytokines, such as IL-4, IL-5, IL-10, and IL-13, and thus drives to development of allergies." (PMID 25960757, 2015). "Th2 cytokines are known to promote the immune response to parasites: IL-4 and IL-13 play a role in the induction of allergy as they stimulate B-cell growth and IgE production, whilst IL-5 typically induces eosinophil differentiation and growth." (PMID 26582546, 2015). "Th2 immune response is linked to protection against helminths and bacteria, whereas the regulatory cytokines IL-4 and IL-5 have prominent roles in allergic diseases." (PMID 26588473, 2015). "During the pathogenesis of allergic disease, IL-4 is crucial for the induction of IgE synthesis and mast cell development." (PMID 25960618, 2015). "The IL-4 stimulates production of antibody-producing B cells, leading to the production of immunoglobulin (Ig), and class-switching to IgE in allergic disease." (PMID 26973760, 2015). "IL-10 has a role in anergy as well as in immune suppression, whereas IL-4 plays a predominant role in allergy." (PMID 25541655, 2014). "Orally administered heat-killed Lactobacillus pentosus strain S-PT84, which is a IL-12-inducing LAB, lowered serum IgE levels and splenic IL-4 production in OVA-induced allergy BALB/c mice." (PMID 24936861, 2014). "Increase in production of Th1 cytokines, IL-12 and IFN-γ as well as decrease in Th2 cytokines, IL-4 and IL-5 by LcS contributed to the prevention of seasonal allergy in Japan." (PMID 24936861, 2014). "They report similar roles for CD8+ and CD4+ cells via the production of cytokines, such as IL-4, or other inflammatory mediators, which is typical of allergic disease." (PMID 25050125, 2014). "Immune regulatory Th2 cytokines, such as IL-4, IL-6, and IL-10, which favor humoral immunity, mediate allergic diseases, control chronic infections, and promote adaptive immunity." (PMID 25264680, 2014). "Settings of high levels of IL-4, IL-13 and IL-17 in AR subjects on multiple allergen exposure support the idea of the heterogeneous nature of allergic disease and the role of Th1/Th2/Th17 balance in the pathogenesis of AR." (PMID 24428928, 2014).
Allergy (continued). "Interleukin-4 (IL-4) is an anti-inflammatory cytokine that is produced and secreted by type 2 T-helper cells and mast cells, and that plays a crucial role in allergic reactions of the skin and mucosa membrane." (PMID 25120668, 2014). "Type I allergic reactions depend on B-cell differentiation and IgE production and histamine release from mast cells induced by IL-4 and IL-13 which helper T cell type II and mast cell produce." (PMID 25276443, 2014). "Th2 cells mainly secrete IL-4, IL-5, IL-6 and IL-10, which are involved in humoral immune and allergic reactions." (PMID 24520300, 2014). "Treatment of HConEpiC with IL-13 or IL-4 alone resulted in an increase in the levels of the allergy-related chemokine eotaxin-3 in the conditioned media at all three doses tested for IL-4 and the highest two doses for IL-13 (10 and 100 ng/ml) after 24 h." (PMID 23878502, 2013). "An additional component of this study was a direct comparison of the cytokines induced by the allergy-related mediators IL-4/IL-13 with TNF-α in two surface ocular cell types, HConEpiC and HConF." (PMID 23878502, 2013). "Based on these results, to determine the effects of mapracorat on allergy-related cytokines, a combination of IL-4 plus TNF-α was selected for the HConEpiC, and IL-13 plus TNF-α was used for the HConF." (PMID 23878502, 2013). "In allergy, the immune system is dysregulated with a predominately Th2-biased response characterized by increased levels of IgE and cytokines such as IL-4 and IL-13 while IgG levels and Th1 cytokines such as IFN-γ are reduced." (PMID 24324465, 2013). "For example, interleukin-4 is a key cytokine that induces naïve T-helper cells to differentiate into T-helper 2 cells, which play a major role in the development of allergies." (PMID 23383309, 2013). "The use of IL-4Rα −/−, IL-13Rα1 −/−, γc −/− and IL-13Rα2 −/− mice have shown that these receptors are indeed important for controlling functions of IL-4 and IL-13 in allergic diseases and parasitic infections." (PMID 23383283, 2013). "Th2 cells and their cytokines (IL-4, IL-5 and IL-13) are abundant in allergic disease, and these cytokines play a central role in initiating allergic inflammation." (PMID 24330349, 2013). "Other studies indicated that fasting and DR can protect the increase of allergen-specific IL-4-producing T cells and suppress the allergic reaction and in humans can ameliorate T-cell function." (PMID 23986784, 2013). "Th2 T cells: CD4+ T cells that express T-helper 2 (Th2)-type cytokines, such as interleukin (IL)-4, IL-5 and IL-13, and mediate immune responses in allergic diseases and parasitic infections." (PMID 23828644, 2013). "IL-4 and IL-13 are closely related cytokines mostly studied for their involvement in allergic diseases (e.g. asthma) and parasitic infections." (PMID 23383283, 2013). "The levels of Th2 cytokines, including IL-4, IL-5, and IL-13, typically increase during an allergic disease." (PMID 23843865, 2013). "These pathologic processes of allergic reaction are thought to be mediated by Th2-type cells, which preferentially produce IgE-enhancing cytokines such as IL-4 and IL-5." (PMID 22876123, 2012). "Intermittent allergic rhinitis and bronchial asthma belong to the group of allergic diseases mediated by Th2-type cytokines, such as IL-4, IL-5, IL-13." (PMID 22349136, 2012). "Spleen cells from both the peanut- and the spinach-treated mice secreted more allergy-promoting interleukin-4 than controls (p<0.01, n=7-24/group)." (PMID 22230662, 2011). "Elevated IL-4, allergen-specific IgE and IgG1 are well recognized principal immune mediators of IgE-mediated allergy." (PMID 22145744, 2011). "It has been reported that p38 MAPK activation can activate transcription factors that result in the expression of IL-4, IL-5, and IL-13 in human T cells in response to antigen exposure in allergic disease." (PMID 21303540, 2011).
Allergy (continued). "Cytokines, such as IL-4 and IL-5, are representative markers of the allergic reaction, based on their roles against allergens." (PMID 21303540, 2011). "Type 2 response is related to secretion of IL-4, IL-5, IL-9 and IL-13 which promote induction of IgE and allergic response." (PMID 20184725, 2010). "In fact, human and mice basophils have been demonstrated to have more IL-4 per cell than T cells and to be responsible for IL-4 secretion in allergic reactions." (PMID 20552026, 2010). "In fact, a daily low intake in healthy volunteers of 60 ml AndoSanTM for 12 days gave a significant 50% reduction in levels of the allergy-promoting cytokine IL-4 in blood and left the other allergy-related cytokines IL-5, IL-7 and IL-13 at negligible levels." (PMID 19416507, 2009). "Allergic diseases are characterized by the presence of Th2 cells and related cytokines, such as interleukin-4 (IL-4), IL-5, IL-9, and IL-13 with the subsequent development of eosinophils infiltration and chronic inflammation." (PMID 16677403, 2006). "In animal models of allergic disease, it has been established that Th2 responses are mediated by T helper cells that secret cytokines such as IL-4 and IL-5, which induce antibody production in B cells, and IgE plays a central role in allergic responses." (PMID 16504003, 2006). "Previous reports have mentioned a positive correlation between IL-4 positive mast cells and the wheal size; antigen specific IgE levels and cutaneous allergic reactions." (PMID 16919166, 2006). "Delineating the molecular mechanisms responsible for the IL-4 induction of TARC expression will be important for a better understanding of the role of Th2 cytokines in allergic disease." (PMID 17134490, 2006). "Unlike TH1 cytokines that directly affect the stress axis, TH2 cytokines, especially IL-4 and IL-13, are involved in the isotype switching from IgM to IgE, which is the antibody responsible for the generation of classical allergic reactions." (PMID 16759987, 2006). "Moreover, toll like receptor 2 ligand promotes the chronic activation of IL-4-dependent Th2 response in a mouse allergy model." (PMID 41576104, 2026). "IL-4 and IL-13 secretion and subsequent binding to their receptor plays a major role in the development of the Th2 immune response and driving the pathogenesis of allergy." (PMID 40004029, 2025). "Furthermore, our aim was to elucidate the correlation between IGM, allergy, and immunological factors through the assessment of interleukin-4 (IL-4), IL-4 receptor (IL-4R), histamine, and histamine-releasing factor (HRF)." (PMID 39941611, 2025). "No elevation of IL‐4, a cytokine implicated in allergy, was detected in the 24 h following treatment in Patient A, nor in any other patient treated with MOv18 IgE." (PMID 40045925, 2025). "Previous literature has shown that basophils can secrete IL-4 in response to allergic reactions." (PMID 40443683, 2025). "Given that the levels of cytokines, including IL-4 and IL-13, are significant biological markers of allergic diseases like AD, our findings indicate that the pre-application of PPE led to a reduction in cytokine release and an improvement in the atopic damage observed in the goat AD model." (PMID 39943182, 2025). "Specifically, Th2 cells secrete cytokines, such as IL-4, IL-5, and IL-13, which promote IgE production by plasma cells, eosinophil activation, and disruption of mucosal barriers, thereby playing a central role in the pathogenesis of allergic reactions." (PMID 39781535, 2025). "The studies show that various compounds, such as linoleic acid, α-linolenic acid, ethyl linoleate, ethyl linolenate, and ethyl stearate, isolated from the mini kiwi fruits, have potential as inhibitors of IL-4 production, which correlates with the occurrence of allergic diseases." (PMID 41375275, 2025).
Allergy (continued). "IL-4 and IL-13 are involved in the inflammatory process of allergic reactions by regulating Th2 cell differentiation and stimulating IgE production by B cells, while IL-10 inhibits Th1 cell activation and proliferation, shifting the immune response to the Th2 type." (PMID 40038782, 2025). "The IL-4/IL-13 pathways are involved in Th2 inflammatory responses and allergic reactions." (PMID 40607391, 2025). "IL-4-dependent eosinophil recruitment leads to elevated inflammation in allergic diseases." (PMID 41293244, 2025). "Dupilumab, a monoclonal antibody targeting the interleukin-4 receptor α (IL-4Rα), blocks the signalling of both IL-4 and IL-13, key mediators of the Th2 inflammatory axis involved not only in atopic dermatitis but also in the development of other allergic diseases such as asthma." (PMID 41002407, 2025). "IFNG and IL4 are involved in immune responses, including allergies and antibacterial responses." (PMID 36658343, 2024). "STAT6 deficiency could also have other Treg-stabilizing effects such as inhibition of the IL-4 mediated conversion of iTregs to Th2-like effector T cells that typically occurs in allergy settings." (PMID 38700792, 2024). "As the results, we found that SAE immunotherapy reduced systemic allergy symptom scores, serum IL-4 levels, IL-4 and FcεR1α mRNA relative expression, and mast cell degranulation in ileum tissue in allergic mice while increasing Foxp3 and IL-10 mRNA relative expression." (PMID 39729447, 2024). "In addition, IL-4 antagonist has a stronger effect than IL-5 antagonist in alleviating allergy-mediated ETD." (PMID 38274710, 2024). "It has been demonstrated that T cells in patients with EoG differentiated to IL-4-IL-5+ Th2 cells, while the IL-4+IL-5- subpopulations were dominant in allergic patients, which may explain, at least in part, the different pathophysiology of allergy and EGIDs." (PMID 39136025, 2024). "IL-4 is involved in IgE production and the pathogenesis of several aspects of allergic disease." (PMID 39684703, 2024). "Previous study has suggested that HSP70 may exert protective effects in allergic diseases, such as downregulating eosinophilia, reducing Th2 cytokines (e.g., IL-4, IL-5, IL-13), and lowering allergen-specific IgE levels." (PMID 39640897, 2024). "In short, IL-4 is responsible for initiating allergic reactions and producing IgE." (PMID 38274710, 2024). "For example, arachidonic acid plays a crucial role in allergic diseases, as it generates leukotrienes and prostaglandins, such as prostaglandin E2, which can induce the production of Th2-type cytokines, such as IL-4, IL-5, and IL-13, as well as the synthesis of IgE." (PMID 38378549, 2024). "IL-4 and IL-5 are 2 important Th2 cytokines that are involved in IgE-mediated allergic reactions." (PMID 38274710, 2024). "IL-4, IL-5 and IL-13 are responsible for the production of non-opsonizing antibodies, allergic reactions, and the suppression of inflammatory reactions caused by Th1 cytokines." (PMID 38787374, 2024). "It was also shown that methylation profile of IL4, IL5, IL10, IFNG and FOXP3 was associated with environmental exposures and the direction of methylation dynamics differed depending on the presence and types of allergy symptoms." (PMID 37520545, 2023). "The expression of the pro-inflammatory cytokine IL-4, which was increased in the allergy model group, was significantly suppressed by fructan administration, and the expression of the anti-inflammatory cytokine IL-10 was significantly increased upon Kes administration." (PMID 37737162, 2023). "Serum IL-4, a cytokine characteristically implicated in allergy, did not change with MOv18 IgE treatment in either animal models or patients." (PMID 37491373, 2023). "Furthermore, 2LALERG® includes ULD of IL-4, IL-5, IL-6, and IL-13 to down-regulate the expression and/or secretion of these well-known allergy-related ILs." (PMID 36675006, 2023).